HNF4A (hepatocyte nuclear factor 4 alpha)
Diseases named in the same sentence as HNF4A in open-access papers (continued):
Sharing a sentence is not in itself a finding about the gene and the disease.
gastric cancer (continued). "We have examined many cell surface receptors after HNF4α knockdown in gastric cancer cell lines." (PMID 26870992, 2016). "Additionally, HNF4α expression in gastric cancer cells, especially in AGS, BGC-823 and SGC-7901, was found to be higher than that in immortalized epithelial cell GES-1." (PMID 26870992, 2016). "As our research deepens the understanding of HNF4α's involvement in the progression through various stages of gastric cancer, including the changes in expression pattern and the variation of isoforms, HNF4α emerges as a possible game-changing molecule that requires further study." (PMID 26870992, 2016). "Interestingly, HNF4α has been shown to act as an oncogene in gastric cancer and only P2-HNF4α is expressed in the stomach." (PMID 27166517, 2016). "In addition, administration of recombinant ITLN1 protein (1 and 2 μg/ml) into cultured gastric cancer cell lines also markedly induced the HNF4α expression at 24 and 36 hrs post-administration." (PMID 25965823, 2015). "In clinical gastric cancer tissues, HNF4α expression was positively correlated with that of ITLN1." (PMID 25965823, 2015). "Gastric cancer patients with high ITLN1 or HNF4α expression had improved survival probability." (PMID 25965823, 2015). "Notably, there was a positive correlation between ITLN1 and HNF4α transcript levels in gastric cancer tissues (correlation coefficient R = 0.819, P < 0.001), which was consistent with the results from public datasets." (PMID 25965823, 2015). "In addition, restoration of HNF4α expression prevented the gastric cancer cells from ITLN1-mediated changes in these biological features." (PMID 25965823, 2015). "Analysis of microarray profiles from patients obtained from Ruijin Hospital at Shanghai Jiao Tong University revealed downregulation of HNF4A expression in gastric cancer (GC) patients (see Part C of SI)." (PMID 38849404, 2024). "Chang and coworkers found hepatocyte nuclear factor-4α (HNF4α) as a key component among multiple expression datasets of gastric cancer (GC) in whole-transcriptome profiles in Caucasians." (PMID 37681914, 2023). "Moreover, a recent study has suggested a role for HNF4α in chemoresistance in gastric cancer, in which they reported that HNF4α may enhance multidrug resistance by regulating cell apoptosis and expression of B-cell lymphoma 2 (Bcl-2)." (PMID 30867652, 2019). "HNF4α gene could serve as a “proto-oncogene” in gastric cancer development." (PMID 30405404, 2018). "Therefore, HNF4α, a nuclear receptor that activated the expression of genes involved in glucose, fatty acid and cholesterol metabolism, was also involved in the development of gastric cancer." (PMID 30405404, 2018). "We also showed the significance of regulation of HNF4α, as well as reduced HIF1α, in early gastric cancer (GC), as detected only by our PATHOME algorithm." (PMID 29050243, 2017). "Koyama and colleagues demonstrated that HNF4A could distinguish all primary gastric carcinomas from metastatic breast carcinomas, suggesting that HNF4A may be a highly useful marker for excluding metastatic breast carcinoma in the diagnosis of gastric specimens." (PMID 28583188, 2017). "Finally, endogenous HNF4α expression, both mRNA and protein, was altered by over-expression and knockdown of NFκB in gastric cancer cells, suggesting that NFκB may regulate the HNF4α expression by repressing its transcription." (PMID 25965823, 2015). "In addition, we found that HNF4α inhibited the nuclear translocation and transcription activity of β-catenin, and suppressed the growth and aggressiveness of gastric cancer cells, suggesting the crucial roles of HNF4α in the tumorigenesis and progression of gastric cancer." (PMID 25965823, 2015). "Importantly, western blot and real-time quantitative RT-PCR indicated that ectopic expression or knockdown of NFκB-p65 decreased and increased the expression of HNF4α, respectively, and prevented the gastric cancer cells from ITLN1-mediated changes in HNF4α expression." (PMID 25965823, 2015).
gastric cancer (continued). "HNF4A and the related HNF1A factor are the most up-regulated transcription factors of the network in the gastric cancer cohort, with a mean expression (normalized mRNA expression z score) of 0.711 and 0.866, respectively." (PMID 41425714, 2025). "Based on these findings, the authors suggested a tumor-suppressive role for omentin-1 in gastric cancer, acting through inhibition of PI3K/NF-κB signaling, restoration of HNF4α, and suppression of β-catenin activity." (PMID 41149627, 2025). "The GEPIA database was then utilized to further assess these TFs, highlighting HNF4A and RARA as highly expressed in stomach cancer (STAD), with subsequent analyses indicating a significant positive correlation between HNF4A and TYMS." (PMID 41326348, 2025). "In this study, knockdown of HNF4α in SGC7901 cell line slowed its proliferation, induced S phase arrest, dramatically attenuated gastric cancer cells metastasis and invasion and suppressed the tumor growth in vivo, the same anti-gastric effect as Berberine." (PMID 30405404, 2018). "We found that knockdown of HNF4α in SGC7901 cell line slowed its proliferation, induced S phase arrest and dramatically attenuated gastric cancer cells’ metastasis and invasion." (PMID 30405404, 2018). "The results demonstrated that the knockdown of HNF4α in SGC7901 slowed cells proliferation, induced S phase arrest and dramatically attenuated gastric cancer cells’ metastasis and invasion." (PMID 30405404, 2018). "We performed immunohistochemistry analysis of HNF4A, ER, PR and GCDFP-15 in 126 patients divided into three cohorts: primary breast cancer, primary gastric cancer and both types of tumors." (PMID 28583188, 2017). "However, the exact functions of HNF4α in gastric cancer still remain largely unknown." (PMID 25965823, 2015). "To further explore the impacts of ITLN1 on the aggressiveness of gastric cancer cells, we investigated the effects of ITLN1 knockdown and HNF4α restoration on cultured gastric cancer cells." (PMID 25965823, 2015). "The absence of ELF3/HNF4A up-regulation seems to define a subgroup of gastric cancers with high rates of genomic stability and diffuse histology." (PMID 41425714, 2025). "In addition, gastric cancers with CDX2 induction and a parallel induction of HNF4A displayed a higher rate of CIN (83% of cases) compared with all cancers with CDX2 induction (CIN in 63.3% of cases) or the cohort with no CDX2 induction (CIN in 43.1% of cases)." (PMID 39768557, 2024). "HNF4α is highly expressed in both primary gastric cancer and metastasis from gastric cancer to mammary gland, but not in breast cancer, which should be a good marker to distinguish primary and metastatic gastric cancer from breast cancer." (PMID 36249028, 2022). "CLRN3 has been identified as a HNF4A transcriptional target in iPSC-derived hepatocytes, and CLDN18 has been confirmed as a GATA6 target in gastric cancer; therefore, we used these likely targets to test the regulatory potential of HNF4A and GATA6 in OE19 cells." (PMID 30962179, 2019). "Our results showed that BBR and knockdown of HNF4α suppressed the growth of SGC7901 in nude mice, HNF4α played a critical role in gastric cancer development and might serve as a potential therapy biomarker." (PMID 30405404, 2018). "This phenomenon indicated that HNF4α may be the downstream of AMPK and BBR could regulate the AMPK/HNF4α pathway in gastric cancer cells." (PMID 30405404, 2018).
gastric cancer (continued). "The expression of HNF4α is seen in primary gastric adenocarcinomas and in metastases of gastric carcinoma to the breast, but is absent in primary breast carcinomas, and in metastases of breast carcinomas to the stomach." (PMID 30405404, 2018). "In various diseases of the digestive system, such as gastric cancer or inflammatory bowel disease, the production of HNF4α is not properly regulated." (PMID 27166517, 2016). "Since previous studies indicate that HNF4α affects the growth, invasion, and metastasis of cancers, and combining the evidence that ITLN1 regulated the HNF4α expression, we further investigated the effects of ITLN1 over-expression and target gene restoration on cultured gastric cancer cells." (PMID 25965823, 2015). "Interestingly, both CDX2 and HNF4α possess binding sequences in the promoter of YAP1, and a positive feed-forward loop may be operating in gastric cancers with CDX2 induction." (PMID 39768557, 2024). "HNF4α is upregulated in gastric carcinoma tissues, compared to normal gastric mucosa." (PMID 39768557, 2024). "HNF4α antagonists, such as BBR, could be a promising anti-gastric cancer treatment supplement." (PMID 30405404, 2018). "Moreover, HNF4α could regulate WNT-β-catenin-E-cadherin signaling to attenuate the growth, invasion and metastasis of gastric cancer." (PMID 30405404, 2018). "However, an altered expression pattern of promoter-driven HNF4α is observed in gastric carcinomas where the diseased gastric mucosa expresses P1 promoter-driven HNF4α as opposed to the normally-expressed P2 promoter-driven HNF4α44." (PMID 27609464, 2016). "Moreover, HNF4α is expressed in human gastric cancer, and absence of HNF4α expression is related to tumor invasion." (PMID 25965823, 2015). "In addition, the activity of nuclear factor-kappa B (NFκB), a transcription factor repressing the expression of HNF4α, is attenuated by ITLN1 via inactivation of phosphoinositide 3-kinase (PI3K)/AKT/Ikappa B kinase (IKK) signaling, suggesting the tumor suppressive roles of ITLN1 in gastric cancer." (PMID 25965823, 2015). "Moreover, restoration of HNF4α expression rescued the gastric cancer cells from ITLN1-mediated suppressive phenotypes, suggesting that ITLN1 may exert its tumor suppressive function, at least in part, through up-regulation of HNF4α in gastric cancer." (PMID 25965823, 2015). "The overall survival (OS) of the two groups of gastric cancers with and without ELF3 and HNF4A concomitant up-regulation was not different (Log Rank test p = 0.24)." (PMID 41425714, 2025). "The high level of CIN in gastric cancers with up-regulation of ELF3 and HNF4A is a feature not currently clinically targetable, but efforts to develop drugs are ongoing." (PMID 41425714, 2025). "Next, a comparison of the sub-set of gastric cancer patients with up-regulated expression of ELF3 and HNF4A with patients who displayed no ELF3 and HNF4A mRNA up-regulation was performed." (PMID 41425714, 2025). "On the other hand, the group of gastric cancers with CDX2 and HNF4A induction had lower prevalence of MSI and no cases with EBV association." (PMID 39768557, 2024). "High co-expression of ELF3 and HNF4A is shown in the current study to lead predominantly to gastric cancers with intestinal histology, lower grade, commonly earlier stage, and the CIN phenotype compared with cancers without up-regulated ELF3/HNF4A co-expression." (PMID 41425714, 2025).
colorectal cancer (36 papers, 2010 to 2025). A primary or metastatic malignant neoplasm that affects the colon or rectum. "Specifically, lncRNAs, such as LINC00858 in colon cancer, LOC100996425 in prostate cancer and LINC00511 in colorectal cancer, were shown to induce tumorigenesis and cancer progression via regulation of HNF4α and associated signaling pathways such as AMPK/mTOR." (PMID 39199690, 2024). "HNF4A (hepatocyte nuclear factor 4-alpha) is an important regulator of metabolism, cell junctions, and the differentiation of intestinal epithelial cells and has been previously associated with colorectal cancer proteomic subtypes in human tumors analyzed by the CPTAC consortium." (PMID 28854368, 2017). "The chromatin-remodelling enzyme ATRX and the transcription factor HNF4A are identified as pivotal regulators of colonic epithelial identity, with roles in metastasis in colorectal cancer." (PMID 40468074, 2025). "Collectively, our study defines the epigenetic maintenance of colonic epithelial identity by ATRX and HNF4A as suppressors of lineage plasticity and metastasis in colorectal cancer." (PMID 40468074, 2025). "For instance, HNF4A, a well-established gastrointestinal-specific transcription factor, ranked as the second most enriched TF in colorectal cancer-specific CREs." (PMID 38213995, 2024). "The chromatin accessibility of HNF4A is significantly elevated in liver metastasis, suggesting an important role for HNF4A in colorectal carcinoma progression." (PMID 39872661, 2024). "In humans, HNF4α P1 isoform is downregulated in colorectal carcinoma at the transcriptional and proteinic level by WNT/β-catenin activity, whereas P2 isoforms are maintained throughout tumorigenesis." (PMID 37974020, 2023). "In this review, we summarized the role and mechanism of HNF4α in different types of cancers, especially in liver and colorectal cancer, aiming to provide additional guidance for intervention of these diseases." (PMID 36249028, 2022). "HNF4A is specifically found in colorectal carcinomas, and its coding gene has two isoforms, P1- and P2-HNF4A." (PMID 36213507, 2022). "They confirmed these interactions by co-immunoprecipitation with endogenous HNF4α in colorectal cancer cell lines." (PMID 32477404, 2020). "The HNF4A locus is amplified in CRC tumors and its overexpression is associated with specific subtypes of colorectal cancer." (PMID 33552987, 2020). "HT-29 and LoVo colorectal cancer cell lines were chosen since they both expressed the endogenous HNF4α." (PMID 31060309, 2019). "One study found that some HNF4α isoforms are lost in 40% of colorectal cancers, while another study found a general upregulation of HNF4α in their samples." (PMID 31216773, 2019). "Several of these proteins including PARP1, RAD50, and DNA-PKcs were confirmed to interact with HNF4α in colorectal cancer cell lines." (PMID 31060309, 2019). "In detail, the function of HNF4A (hepatocyte nuclear factor 4 alpha) in colorectal cancer was controversial." (PMID 30546056, 2018). "Two cases showed diffuse and strong staining for HNF4α, as seen in mucinous adenocarcinoma or colorectal carcinoma." (PMID 28830562, 2017). "Among them, expression of HNF4A is increased by alternative promoters in several cancers such as liver, gastric, and colorectal cancers." (PMID 27016420, 2016). "Down-regulation of HNF4α is also involved in the metastasis and worse prognosis of colorectal cancer." (PMID 25965823, 2015). "Overall our data suggests that a regulatory feedback loop between miR-124 and PKM1/HNF4α exists and is essential for apoptosis regulation in colorectal cancer cells." (PMID 24619225, 2014).
colorectal cancer (continued). "Studies exploring HNF4α induction demonstrated that this transcription factor inhibits liver cell proliferation, while its inhibition promotes tumorigenesis in liver and colorectal cancers." (PMID 41244070, 2025). "For example, HNF4A, which controls epithelial cell differentiation and homeostasis, was overrepresented in yMB, whereas NFYA, which was underrepresented in yMB, has been linked to gastric adenocarcinomas and aggressiveness of colorectal cancer." (PMID 40176137, 2025). "HNF4A exhibited the highest expression levels in both colorectal cancer tissues and cell lines, regulated many target genes and was essential for the viability of the majority of colorectal cancer cells in the unbiased high-throughput CRISPR screening." (PMID 38213995, 2024). "Beyond the liver, roles for HNF4α have been identified in several malignant and pre-malignant lesions including Barret’s esophagus, gastric intestinal metaplasia, gastric adenocarcinoma, colorectal carcinoma and PDAC13,14." (PMID 37974020, 2023). "Furthermore, transcription factors such as Heat Shock Transcription Factor 1(HSF1) and Double-Strand-Break Repair Protein Rad21 Homolog (RAD21) play a regulatory role with HNF4α in colorectal cancer metastasis." (PMID 36249028, 2022). "Both HNF4α and oxidoreductase related genes are overexpressed in colorectal cancers." (PMID 36249028, 2022). "In colorectal cancer, KRAS mutations in cluster 9458.0 affecting p.G12, p.G13, p.V14, and p.Q61 are associated with higher KRAS expression, whereas HNF4A mutations in cluster 7977.0 are associated with low HNF4A expression." (PMID 33875650, 2021). "BioID with P2-HNF4α-BirA∗ and immunoprecipitation with P2-HNF4α-GFP in HEK293T or HCT116 (colorectal cancer cell line without HNF4α expression) revealed an association of P2-HNF4α with DNA repair factors including PARP1, RAD50, and PRKDC." (PMID 32477404, 2020). "HNF4A was identified as a transcriptional activator for intestinal differentiation and gene expression of HNF4A and its target genes were upregulated in colorectal cancer cell lines with a more epithelial phenotype, as compared to cells with a mesenchymal phenotype." (PMID 30909444, 2019). "Following DNA damage, HNF4α was able to increase cell viability in colorectal cancer cells." (PMID 31060309, 2019). "Considering the significant roles of NRs in cancer development and the high expression of HNF4α in gastrointestinal cancers, such as colorectal carcinoma, we investigated whether HNF4α regulated the biological behaviors of pancreatic cancer." (PMID 30867652, 2019). "Hnf4a is reported to be important for intestinal epithelial homeostasis by modulating Wnt signaling and can act as a tumor suppressor in colorectal cancer." (PMID 29945941, 2018). "Moreover, HNF4α or PKM1 had a more dramatic effect on colorectal cancer cell apoptosis in the presence of miR-124." (PMID 24619225, 2014). "PKM1 or HNF4α regulating apoptosis of colorectal cancer cells was partially via miR-124." (PMID 24619225, 2014). "Another example is the relationship between HNF4a and colorectal cancer." (PMID 23822816, 2013). "Additionally, HNF4α protein levels were evaluated in six commercial colorectal cancer cell lines." (PMID 40277924, 2025). "On the other hand, HNF4α also shows increased expression in clinical samples of HCC, ovarian mucinous carcinomas, colorectal carcinoma, lung mucinous adenocarcinoma, and neuroblastoma." (PMID 31695151, 2020).